FOXM1 (forkhead box M1)
Diseases named in the same sentence as FOXM1 in open-access papers (continued):
Sharing a sentence is not in itself a finding about the gene and the disease.
lung adenocarcinoma (continued). "Importantly, we further demonstrated that the expression levels of FOXM1, pAKT and MET were significantly increased in lung adenocarcinoma tissues relative to normal lung tissues, and these three biomarkers were concomitantly overexpressed in lung adenocarcinoma tissues." (PMID 27494877, 2016). "CD44 positive cells from lung adenocarcinoma patients, compared to CD44 negative cells, have higher metastatic ability mediated by the Wnt/β–catenin–FoxM1–twist pathway." (PMID 34439211, 2021). "The mRNA expressions of FOXM1 and MET were confirmed to be higher in lung adenocarcinoma specimens than in adjacent non-cancerous specimens." (PMID 27494877, 2016). "The protein expressions of FOXM1, MET and pAKT were confirmed to be higher in lung adenocarcinoma specimens than in adjacent non-cancerous specimens." (PMID 27494877, 2016).
colon carcinoma (56 papers, 2009 to 2025). "FoxM1-mediated colon cancer metastasis is linked to regulating E-cadherin, vimentin, Snail expressions." (PMID 26755651, 2016). "FOXM1, a key transcription factor, plays a pivotal role in regulating cell cycle progression and is implicated in various physiological and pathological processes, including cancers like liver, prostate, breast, lung and colon cancer." (PMID 40091487, 2025). "Therefore, FOXM1 is likely associated to the tumor growth, recurrence, and metastasis of colon cancer." (PMID 38967523, 2024). "FOXM1 is a key cell cycle regulator that plays a key role in embryogenesis and cell proliferation and has been strongly linked to solid tumors like colon cancer, where it is linked to reduced disease-free survival, which suggests it is an important prognostic marker." (PMID 39228892, 2024). "FoxM1 overexpression is significantly associated with colon cancer metastasis." (PMID 26755651, 2016). "In summary, our studies have demonstrated that overexpression of FOXM1 is associated with distant lymph metastasis and tumor recurrence, and knockdown of FOXM1 by shRNA inhibited cell proliferation, migration and invasion of human colon cancer cells." (PMID 25935853, 2015). "FOXM1 is commonly regarded as an oncogenic transcription factor and abnormal expression and activation of FOXM1 is associated with the proliferation and metastasis of human colon cancer cells, as an independent poor prognostic factor and conversely correlated with poor OS and MFS in CRC patients." (PMID 25935853, 2015). "The regulatory function of TEAD4, TCF3, ETV4, SOX4, and FOXM1, over other key TFs and common DEGs, was highlighted in colon cancer, establishing key co-regulatory complexes." (PMID 39228892, 2024). "CircCTNNA1 can absorb miR-149 and antagonize its repressive influence on its subsequent target Forkhead Box M1 (FOXM1) to enhance cell proliferation and infiltration in colon cancer." (PMID 37744277, 2023). "The discovery that the AhR represses FOXM1 expression in the colon is consistent with a previous report showing that FOXM1 signaling contributes to formation and growth of colonic tumors." (PMID 38651159, 2023). "The lignan, (−)-(2R,3R)-1,4-O-diferuloylsecoisolariciresinol (DFS), from Alnus japonica has shown anti-cancer effects against colon cancer cells by suppressing FOXM1." (PMID 35978012, 2022). "HCT-116 5FUR cells display downregulation of FOXO3 and increased expression of FOXM1 compared to parental colon cancer cell lines." (PMID 35910798, 2022). "For example, Ozden O. and Parkin S-H demonstrated that SIRT2 affects the expression of oncogenic FOXM1 in HCT116 colon cancer cells leading to a decrease in the number of colony formations and proliferation." (PMID 35326523, 2022). "Thiostrepton was previously considered a thiazole antibiotic and is currently identified as an effective therapeutic drug for colon cancer that targets the oncogenic transcription factor FoxM1." (PMID 36100894, 2022). "Previous studies have shown that FOXM1-TYMS mediates 5-FU resistance of tumor cells in colon cancer." (PMID 35093082, 2022). "For example, the dysregulated FOXM1-PLAUR signaling axis is significantly associated with the progression and metastasis of human colon cancer." (PMID 35991839, 2022). "Nrf2 and FoxM1 expression was increased in colon cancer tissues compared to in adjacent normal tissues." (PMID 34798428, 2021). "The most related mRNA (FOXM1) and CircRNA (CircCTNNA1, a new CircRNA) were significantly up-regulated in colon cancer, and their levels were related to the stage of lymph node metastasis, poor prognosis and poor survival in patients with colon cancer." (PMID 34722295, 2021). "Recently, the possibility of lysosome-mediated FOXM1 degradation was reported in colon cancer cells." (PMID 34262016, 2021). "Nrf2 and FoxM1 expression was upregulated in colon tumor tissues compared to in the adjacent normal tissues." (PMID 34798428, 2021).
colon carcinoma (continued). "We next evaluated RASSF1A and FoxM1 expression in paired colon tumor (CT) and normal tissue (NT) obtained from patient surgical samples." (PMID 30744076, 2019). "An imbalance of activation of cellular oncogenes such as FoxM1 and loss of function of tumor suppressor genes such as RASSF1A promotes colon cancer progression." (PMID 30744076, 2019). "Overexpression and knock-down studies of FOXM1 in colon cancer cells suggest the importance of FOXM1 in TYMS regulation." (PMID 30728402, 2019). "Immunohistology showed a significant increase of FoxM1 staining with progression of colon cancer stages combined with a decrease in RASSF1A expression (B p < 0.01 to p < 0.001)." (PMID 30744076, 2019). "In the array, we observed FOXM1 positive staining in both the cytoplasm and nuclei of the majority of cancer cells (>90%), indicating that FOXM1 is commonly overexpressed in human colon cancer." (PMID 30728402, 2019). "(B) According to UALCAN database, the Kaplan-Meier survival curve demonstrates high expression of FoxM1 in colon cancer correlated with poor survival." (PMID 31234887, 2019). "To conclude, in this study, we have demonstrated for the first time that FOXM1 has a crucial role in 5-FU drug resistance in colon cancer cells, through regulating some of the main 5-FU targets, including TYMS, TK-1 and TYMP." (PMID 30728402, 2019). "The FoxM1 destabilizing activity of DFS was also confirmed in cycloheximide-treated colon cancer cells." (PMID 28378765, 2017). "To assess the mechanism of the action of DFS, we investigated the effect of DFS on endogenous and exogenous FoxM1 protein degradation in colon cancer cells." (PMID 28378765, 2017). "Presently, DFS mediated FoxM1 degradation by activating lysosomal-mediated degradation, which reduced the viability of colon cancer cells in culture and in vivo in a mouse xenograft model." (PMID 28378765, 2017). "Knock-down of PSMA3 (20S proteasomal protein), PSMD3 (19S proteasomal protein), and PSME1 (11S proteasomal protein) resulted in increased size and quantity of FoxM1 compared with control colon cancer cells (brace)." (PMID 28378765, 2017). "DFS-induced FoxM1 degradation was blocked by treatment with chloroquine in colon cancer cells, while the levels of Notch 3 and E-cadherin were not changed by DFS." (PMID 28378765, 2017). "Treatment with chloroquine slightly restored FoxM1 levels in cycloheximide-treated colon cancer cells, which means that FoxM1 degradation is partially dependent on the lysosome under normal conditions." (PMID 28378765, 2017). "The in vivo tumor xenografts also provided evidence that PTTG1 participates in the FoxM1-mediated liver metastases of colon cancer." (PMID 26264222, 2015). "In present study, we identified PTTG1 as a FoxM1 target gene in colon cancer, which provides a mechanism of FoxM1 involved in the metastasis of malignances." (PMID 26264222, 2015). "To further confirm the expression of FoxM1 in colon cancer, we detected the expression of FoxM1 in fresh colon cancer tissues, metastatic lymph nodes and adjacent normal tissues from four same patients." (PMID 25935853, 2015). "Previous research had revealed the role of FOXM1 in cell growth; increased expression of Foxm1 in Rosa26-Foxm1b transgenic mice directly regulated the cell-cycle progression of colon tumor cells by promoting S-phase progression and entry into mitosis." (PMID 25935853, 2015). "The actual occurrence of EMT serves as a dominant role in invasion and metastasis of colon cancer, which is regulated by a various signal pathways, such as FOXM1-PLAUR, FOXM1-caveolin-1 signaling pathway." (PMID 25935853, 2015). "To investigate the role of PTTG1 and FoxM1 in colon cancer metastasis, we stably expressed FoxM1 in PTTG1+/+ and PTTG1−/− HCT116 cells, and implanted these cells into the spleen of nude mice to induce liver metastases." (PMID 26264222, 2015). "In colon cancer, FOXM1 activates transcription of PRX3 and CD133 in the cancer stem cells." (PMID 38967523, 2024).
colon carcinoma (continued). "AhR-dependent repression of FOXM1 was observed in crypts adjacent to colon tumors and tumors, stem and progenitor cells and chromatin immunoprecipitation showed that TCDD induced formation of the AhR:ARNT complex in regions of the FOXM1 promoter containing a cis-acting AhRE binding site." (PMID 38651159, 2023). "•Nrf2/FoxM1-induced Srx-Prx redox system is a target to eliminate CSCs in colon cancer." (PMID 34798428, 2021). "Therefore, the Nrf2/FoxM1-induced Srx-Prx redox system is a potential therapeutic target for eliminating CSCs in colon cancer." (PMID 34798428, 2021). "Hence, considering their roles in cancerous cells and CSCs, we first verified Nrf2 and FoxM1 expression in colon cancer tissues and adjacent normal tissues using qRT-PCR." (PMID 34798428, 2021). "MiR-320 by targeting FOXM1 could enhance the sensitivity of human colon cancer cell to 5-Fu and Oxaliplatin and induce cell cycle arrest at G0/G1 phase." (PMID 33330110, 2020). "Moreover existence of an inverse correlation between RASSF1A, a tumor suppressor of the RAS signaling pathway, and FOXM1 has been observed in the progression of colon cancer." (PMID 33680951, 2020). "Furthermore, Kaplan-Meier survival curves revealed that high expression of FoxM1 in colon cancer correlated with poor survival (P < 0.05)." (PMID 31234887, 2019). "FOXM1 expression has also been associated with resistance to chemotherapy and to ionizing radiation of GBM cells, unlike FOXN3 which inhibited growth, migration and invasion of colon cancer cells and the proliferation of HCC cells." (PMID 30167084, 2018). "Interestingly, FOXM1 transactives PLAUR expression to promote colon cancer progression and metastasis." (PMID 27259253, 2016). "Taken together, our current study strongly suggests that FOXM1 signaling has important roles in CRC cells proliferation and aggressiveness; thus, it is indicated that an intervening strategy targeting FOXM1 signaling in colon cancer may be of clinical value." (PMID 25935853, 2015). "Moreover, the FOXM1-PLAUR axis contributed to colon carcinomas." (PMID 33892811, 2021). "For example, PRX3 induced by FOXM1 could maintain the mitochondrial function of colon cancer cells." (PMID 33754036, 2021). "Mechanistically, forkhead box M1 (FOXM1) expression is enhanced by H3K79me2 that is present in both tumor cells and DCs, which causes abnormal maturation phenotypes of DCs and decreased production of IL-12 in tumor-bearing mice with pancreatic and colon cancers." (PMID 33868269, 2021). "However, DFS reduced FoxM1 protein levels in proteasomal protein knock-down colon cancer cells." (PMID 28378765, 2017). "Furthermore, we recently reported that FoxM1 binds to the Prx3 promoter in colon cancer." (PMID 29190956, 2017). "Here, we showed that treatment with UroA or UAS03 in 5FUR colon cancer cells significantly induced FOXO3 expression and downregulated FOXM1, which in turn is potentially responsible for downregulation of drug transporters." (PMID 35910798, 2022). "In sync with that, FOXM1-dependent upregulation of PKM2 promotes glycolysis and the Warburg effect in colon cancer." (PMID 35794249, 2022). "On the other hand, increased transcriptional activity of FOXM1 was mediated through the dimethylation of H3K27 by DOT1L in pancreatic and colon cancer." (PMID 33680951, 2020). "As FoxM1, abnormal transcription and expression of PTTG1 is involved in colon cancer progression and metastasis and is a FoxM1 targeted gene." (PMID 30744076, 2019). "Elevated FOXM1 and TYMS expression was also observed in acquired 5-FU resistant colon cancer cells (HCT116 5-FU Res)." (PMID 30728402, 2019).
colon carcinoma (continued). "We further evaluated FoxM1 and RASSF1A expression in CRC using tissue arrays containing the specturm of colon cancer stages (stage I–IV) as well as normal colon tissue (NAT)." (PMID 30744076, 2019). "We therefore decided to study the expression of FOXM1, TYMS, and E2F1 in colon cancer cell lines, following treatment with 2 μM of thiostrepton for 24, 48 and 72 hours." (PMID 30728402, 2019). "We found that FOXM1 was highly correlated with tumor EMT, and previous studies suggested that FOXM1 regulated the expression of TYMS and mediated the resistance of tumor cells to 5-FU in colon cancer." (PMID 35093082, 2022). "Similarly, miR-122 and miR-320 have re-sensitizing 5-FU-resistant colon carcinoma cells to 5-FU, by modulating pyruvate kinase isozymes 2(PKM2) and forkhead box M1 (FOXM1) actions respectively." (PMID 32503256, 2020). "This is the first report to identify crosstalk between FoxM1 and RASSF1A, which could be used as a novel target to advance colon cancer treatment." (PMID 30744076, 2019). "Previous studies about transcription regulation signaling pathway suggested that FOXM1 transcriptionally regulated of downstream genes such as TGF-β/SMAD3/4 to promote cancer metastasis and induced PRX3 to regulates stemness and survival of colon cancer cells." (PMID 27716361, 2016). "Moreover, Nrf2 and FoxM1 were highly expressed in colon CSCs compared to in non-CSCs isolated from colon cancer patients." (PMID 34798428, 2021). "In addition, Nrf2 and FoxM1 expression was increased in CSCs isolated from colon cancer tissues compared to in non-CSCs." (PMID 34798428, 2021). "DFS decreased the protein level of FoxM1 without changing the mRNA level in colon cancer cells." (PMID 28378765, 2017). "Expression of E2F1 was not affected by FOXM1 overexpressing HCT116 cells, but in thiostrepton treated HCT116 and HT29 colon cancer cells, E2F1 was downregulated, suggesting that E2F1 is regulated by FOXM1." (PMID 30728402, 2019). "In both human colon cancer cell line HCT116‐ and CD14‐positive monocytes, we observed robust ChIP‐seq signals and peaks of H3K4me3 and H3K79me2, but not H3K36me3 on the promoter of FOXM1, suggesting that FOXM1 could be modulated through H3K4me3 and H3K79me2 modification across different cell types." (PMID 30628173, 2019).
melanoma (56 papers, 2009 to 2025). A malignant, usually aggressive tumor composed of atypical, neoplastic melanocytes. "FOXM1, a transcription factor, has been demonstrated to express at higher levels in metastatic melanoma compared with primary melanoma, and the high expression of FOXM1 is associated with lower overall survival." (PMID 35138218, 2022). "Previous studies have shown that higher levels of FOXM1 in tumor tissues have been strongly associated with low prognosis in melanoma patients, consistent with our study." (PMID 33912448, 2021). "Circ-FOXM1 deficiency impeded cell proliferation, invasion, and glycolysis and facilitated cell apoptosis in melanoma in vitro and tumorigenesis in vivo." (PMID 32183822, 2020). "Compared with neonatal human epidermal melanocytes, BRAFV600E-mutated Colo829 human melanoma cells showed enhanced expression of Pin1, FOXM1, CENPF and Cyclin B1 both at the mRNA and protein levels." (PMID 26279295, 2016). "Moreover, our data exhibited that circ-FOXM1 deficiency repressed cell proliferation, metastasis, and glycolysis and facilitated apoptosis in melanoma by miR-143-3p/FLOT axis." (PMID 32183822, 2020). "FOXM1 is a proliferation-associated transcription factor and an essential regulator of oxidative stress that is expressed during cell cycle and it was shown to be overexpressed in melanoma." (PMID 33091721, 2020). "Altogether, these experiments indicate that (I) Pin1 correlates with FOXM1 expression and activity in malignant melanoma, (II) Pin is causally linked to FOXM1 activity through physical binding on MEK/ERK target sites and (III) oncogenic BRAF stimulates the Pin1-FOXM1 interaction through MEK." (PMID 26279295, 2016). "Transcriptome sequencing and bioinformatics analysis identified FOXM1 as the hub gene of lasalocid-mediated melanoma treatment." (PMID 39781349, 2025). "Real-time PCR, Western blot, and immunofluorescence experiments validated the inhibitory impact of lasalocid on FOXM1 in melanoma cells." (PMID 39781349, 2025). "Collectively, the findings indicate that lasalocid exhibits potential as a suppressor of melanoma cell proliferation through the down-regulation of FOXM1 via activation of the JNK/P38 MAPK pathway." (PMID 39781349, 2025). "In other cancer types (NSCLC and melanoma), FOXM1 and AURKB have been reported to suppress immune cell activation." (PMID 40630538, 2025). "This study demonstrates that lasalocid inhibits the proliferation and migration of melanoma cells by downregulating FOXM1 through the PI3K/AKT and JNK/P38 MAPK pathways." (PMID 39781349, 2025). "In summary, our study results emphasize lasalocid's potential as a melanoma therapeutic agent and elucidate its role in regulating FOXM1 through the PI3K/AKT and JNK/P38 MAPK pathways." (PMID 39781349, 2025). "In summary, this study elucidated the molecular mechanism by which lasalocid inhibits melanoma by down-regulating FOXM1 via the PI3K/AKT and JNK/P38 MAPK pathways." (PMID 39781349, 2025). "Collectively, these findings suggest lasalocid suppresses melanoma cell proliferation by down-regulating FOXM1 through activating P38/JNK MAPK pathway." (PMID 39781349, 2025). "The study results indicate lasalocid exerts its anti-melanoma effect by regulating expression of cell cycle, migratory invasion, and apoptosis-related proteins through the FOXM1 pathway." (PMID 39781349, 2025). "Analysis of gene expression in diverse clinical tumor samples has revealed up-regulation of FOXM1 expression in cancer cells, including melanoma." (PMID 39781349, 2025). "Its target Survivin was highly expressed in advanced melanoma disease, as well as FoxM1, which plays an important role in melanoma progression and chemoresistance." (PMID 37372043, 2023). "The results of in vitro research point to the possibility that the PDGFRB and FOXM1 genes function as oncogenes in melanoma." (PMID 36467505, 2022).